TMPRSS2 (transmembrane serine protease 2)
Diseases named in the same sentence as TMPRSS2 in open-access papers (continued):
Sharing a sentence is not in itself a finding about the gene and the disease.
Hearing impairment (1 paper, 2024). A decreased magnitude of the sensory perception of sound. "The presence of ACE2 receptors, TMPRSS2, and Furin in otolaryngological tissues may explain their susceptibility to SARS-CoV-2 infection and subsequent hearing impairment." (PMID 39175987, 2024).
Hypercalcemia (1 paper, 2017). An abnormally increased calcium concentration in the blood. "VDRM2 significantly reduces TMPRSS2:ERG positive VCaP xenograft tumor growth without causing hypercalcemia or significant weight loss in mice and VDRM2 is stable in cells that overexpress CYP24A1." (PMID 28591703, 2017).
Hypokalemia (1 paper, 2020). An abnormally decreased potassium concentration in the blood. "The evidence that hypokalemia triggers expression of TMPRSS2 suggests potassium supplementation as a promising strategy to prevent loss of K+, lung hypertension, normalize cell volume, and prevent TMPRSS2-dependent viral infectivity." (PMID 33142989, 2020). "TMPRSS2 inhibition of ENaC provides a fine-tuning of electrolytes and osmolytes, and protects from hypokalemia." (PMID 33142989, 2020).
in situ carcinoma (1 paper, 2018). A malignant epithelial neoplasm which is confined to the epithelial layer without evidence of further tissue invasion. "This phenomenon was inconsistent with the reports, wherein the frequency of TMPRSS2-ERG fusion was shown to be 50% in in situ carcinoma and decreased in malignant PCa." (PMID 30459527, 2018).
Intellectual disability (1 paper, 2022). "Moreover, we analyzed the three polymorphisms, rs35074065 and rs12329760 in the TMPRSS2 gene and rs333 in the CCR5 gene, in a cohort of patients with intellectual disability residing in rehabilitation departments of the Research Institute “IRCCS Oasi Maria SS”, based in Troina, Italy." (PMID 36012436, 2022).
irritable bowel syndrome (1 paper, 2021). Irritable bowel syndrome (IBS) is a chronic functional condition of the lower gastrointestinal (GI) tract characterized by abdominal pain or discomfort and disordered bowel habit (diarrhea, constipation, or fluctuation between the two). "In patients with irritable bowel syndrome (IBS), the ACE2 and TMPRSS2 expressions in the colonic mucosa are not increased compared to control patients without IBD." (PMID 33391502, 2021).
keratoconus (1 paper, 2021). A degenerative, structural disorder of the eye, characterized by a cone-shaped protrusion of the cornea. "We found that ACE2 and TMPRSS2 expression level were highly correlated with corneas and keratoconus." (PMID 34085038, 2021).
large cell lung carcinoma (1 paper, 2022). "TMPRSS2 was significantly decreased in LUSC, LUAD, lung carcinoid tumor, small cell lung carcinoma, and large cell lung carcinoma." (PMID 35017320, 2022).
mental disorder (1 paper, 2022). A disease that has its basis in the disruption of mental process. "Eight genes are implicated in viral (SEC14L1, JMJD6, SRSF2, TMPRSS2, MX1, MX2) or bacterial (COL8A1, SPIRE1) infections, seven genes (MFSD11, METTL23, CTTNBP2, BACE2, IMPA2, MPPE1 and GNAL) are involved in mental disorders and one gene (MGAT5B) is related to the Golgi complex." (PMID 35581286, 2022).
mesenchymal tumors (1 paper, 2019). "The proportion of repeat regions within the breakpoint cluster regions was 25% for TMPRSS2 and 34% for ERG, which is comparable to other mesenchymal tumors for which DNA-level genomic fusion sequences have been successfully established as patient-specific biomarkers (Supplemental )." (PMID 31915468, 2019).
multiple sclerosis (1 paper, 2022). A progressive autoimmune disorder affecting the central nervous system resulting in demyelination. "Despite the fact that TMPRSS2 proves widely polymorphic in the Madrid familial multiple-sclerosis cohort, only rs75603675 has been linked to SARS-CoV-2 infection." (PMID 35193695, 2022).
oral cancer (1 paper, 2021). "There have also been reports of TMPRSS2 expression in oral cancer and the cell lines." (PMID 33421967, 2021).
pancreatic insufficiency (1 paper, 2021). "Lower ACE2 levels and trends toward the reduction of furin and TMPRSS2 were found in CF patients compared with the healthy controls; decreased ACE2 amounts were also detected in CF individuals with pancreatic insufficiency and in those receiving inhaled antibiotics." (PMID 33401565, 2021).
papillary renal cell carcinoma (1 paper, 2023). A rare subtype of renal cell carcinoma, arising from the renal tubular epithelium and showing a papillary growth pattern, which typically manifests with hematuria, flank pain, palpable abdominal mass or nonspecific symptoms, such as fatigue, weight loss or fever. "A previous bioinformatical study has shown that esophageal squamous cell carcinoma, cervical cancer and papillary renal cell carcinoma express ACE2 and TMPRSS2 mRNA." (PMID 36595529, 2023).
preeclampsia (1 paper, 2020). Preeclampsia is a hypertensive disorder of pregnancy that is characterized by new-onset hypertension with proteinuria presenting after 20 weeks of gestation, and depending on mild or severe forms may initially present with severe headache, visual disturbances, and hyperreflexia. "Beyond preterm births, the demonstration that the ACE2 + TMPRSS2 + subpopulation of EVTs consists of invasive endovascular trophoblasts is clinically relevant in conditions like preeclampsia." (PMID 32974340, 2020).
psoriasis (1 paper, 2025). An autoimmune condition characterized by red, well-delineated plaques with silvery scales that are usually on the extensor surfaces and scalp. "Its therapeutic potential for psoriasis is linked to its ability to target Toll-like receptor (TLR-4) and inhibit the protease TMPRSS2, which plays a role in viral entry." (PMID 40161116, 2025).
pterygium (1 paper, 2021). A wedge-shaped fibrovascular lesion arising from the bulbar conjunctiva and extending to the cornea. "A recent study showed that no consistent TMPRSS2 existence can be found in conjunctival samples, while it is present in some pterygium samples." (PMID 33804977, 2021).
respiration (1 paper, 2023). "Hence, the transfected A549-hACE2 and A549-hACE2-TMPRSS2 that express both ACE2 and/or TMPRSS2 are generated to make them permissive to SARS-CoV-2 and other respiration infections." (PMID 36979955, 2023).
testicular germ cell tumours (1 paper, 2022). "In contrast, the methylation levels of TMPRSS2 promoter in COAD, PRAD, READ and testicular germ cell tumours (TGCT) were relatively decreased than those in normal tissue." (PMID 34951103, 2022).
thyroid neoplasms (1 paper, 2023). "Regarding TMPRSS2 mRNA expression, the distribution was similar between thyroid neoplasms and adjacent normal tissues." (PMID 37568724, 2023).
vitamin D deficiency (1 paper, 2020). A nutritional condition produced by a deficiency of VITAMIN D in the diet, insufficient production of vitamin D in the skin, inadequate absorption of vitamin D from the diet, or abnormal conversion of vitamin D to its bioactive metabolites. "Examples include vitamin D deficiency, poor diets, and differential expression of the enzyme TMPRSS2, among others." (PMID 33025909, 2020).
infection (889 papers, 2011 to 2026). The state of being infected such as from the introduction of a foreign agent such as serum, vaccine, antigenic substance or organism. "A supplementary contribution of other serine proteases was also suggested because the infection of the Delta variant was still inhibited partially by nafamostat in TMPRSS2 KO organoids." (PMID 39601592, 2025). "Experimental investigations involving TMPRSS2−/−-deficient mice and cell cultures have revealed the pivotal role of this host protease in facilitating the effective infection and dissemination of the IAV subtype H10 and H2." (PMID 39858469, 2025). "Nevertheless, haplotype analyses indicated that both alleles seem to contribute to infection, highlighting the importance of allele combinations and the remarkable function of TMPRSS2 in SARS-CoV-2 infection susceptibility." (PMID 40296872, 2025). "Given that supporting cells in the olfactory epithelium abundantly express TMPRSS2, these cells are likely less susceptible to infection by postancestral variants, preserving olfactory function." (PMID 40492581, 2025). "Out of the 24 explored polymorphisms, only some of them in the TMPRSS2 gene were associated with the risk of infection with SARS-CoV-2." (PMID 40296872, 2025). "ACE2 and TMPRSS2 co-localization in oral and airway mucosa accounts for susceptibility via the airborne route of infection, while kidneys, GI tract, and reproductive epithelia show much higher ACE2 levels but with lower susceptibility." (PMID 40631549, 2025). "In TMPRSS2 KO organoids, infection by the Delta variant was inhibited by nafamostat by only ~0.6 log10, which was smaller than that observed in WT organoids (~1.5 log10)." (PMID 39601592, 2025). "The co-expression of TMPRSS2 with the HCoV-229E receptor CD13 in human airway epithelial cells indicates that TMPRSS2 plays an important role in the infection process caused by HCoV-229E." (PMID 40297833, 2025). "After experimental infection, TMPRSS2-deficient strains exhibited less body weight loss and reduced viral kinetics in the lungs." (PMID 39858469, 2025). "In this study, CQ was able to inhibit the A.2.5 variant infection in Calu-3 cells, although at a lower level (two-fold less) compared to the TMPRSS2 inhibitor camostat (CAM)." (PMID 40535766, 2025). "Expression of ACE2 facilitates virus replication in the airway epithelium and increases susceptibility to infection, while TMPRSS2 contributes to the virus entry into cells and promotes its transmission." (PMID 39267977, 2024). "Cells with high ACE2 and TMPRSS2 expression have strong virus binding capacity and are particularly susceptible to infection." (PMID 39126095, 2024). "Similar antiviral effects of HAT against WT strain can be observed in TMPRSS2-positive Calu-3 cells by pseudovirus and authentic infection systems, and the Delta and Omicron variants also showed similar resistance to HAT as in 293T/ACE2." (PMID 39286971, 2024). "On the host side, transcriptional profiling confirmed the magnitude of infection-induced antiviral and proinflammatory responses were linked to uptake efficiency, with TMPRSS2-assisted entry boosting early antiviral responses." (PMID 38814864, 2024). "Previous studies have also described the weakening of fusion activity upon Omicron variant infection in TMPRSS2-expressed cells that correlated to impaired syncytia formation." (PMID 38568894, 2024). "In summary, our orally-available bispecific inhibitor TMP1 simultaneously suppresses the activity of SARS-CoV-2 Mpro and host TMPRSS2 with high potency, thus effectively blocking the infections and transmission of human-pathogenic coronaviruses." (PMID 39606435, 2024). "Further, only mice expressing TMPRSS2 developed lung inflammation and disease manifestations upon infection with the Beta variant, whereas Omicron infection induced some inflammation, even in TMPRSS2−/− mice." (PMID 36851486, 2023).
infection (continued). "While other SARS-CoV-2 variants require the S protein priming by the host transmembrane protein TMPRSS2 for cellular entry, the infection of Omicron variants can be accomplished by an endocytic route in a TMPRSS2-independent manner." (PMID 37381062, 2023). "The number of SARS-CoV-2 Beta-infected lung cells was much lower in TMPRSS2 KO mice, underlining the essential role of TMPRSS2 in infection with the SARS-CoV-2 Beta variant." (PMID 36851486, 2023). "The protective effect of pantethine was associated with a reduction in the infection-induced increases in the expression levels of TMPRSS2 and different HECT E3 ligases, which were proposed to be potential therapeutic targets for SARS-CoV-2 infection." (PMID 36754974, 2023). "In both cell lines we observed an onset of transcription at 4 h post-infection (hpi) for all E484 variants and WT, with an overall higher entry efficiency in the TMPRSS2 expressing Calu-3 cells, corresponding to observations by us and others." (PMID 37940989, 2023). "The absence of expression of proteins encoded by the deleted genes during Vero E6/TMPRSS2 infection was confirmed by immunoblotting." (PMID 37623322, 2023). "Inhibitors targeting TMPRSS2 either in TMPRSS2-deficient cells or in infection with the SARS-CoV-2 Omicron variants are ineffective in preventing infection." (PMID 37126530, 2023). "In sum, our results indicated that expression of the serine protease TMPRSS2 was critical for disease development, upon infection with the Beta variant SARS-CoV-2." (PMID 36851486, 2023). "As proteolytic cleavage of ACE2 by ADAM17 and TMPRSS2 affects susceptibility to infection, it is possible that recent trypsin treatment also impact ACE2 cleavage on target cells." (PMID 36289285, 2022). "We show that subclones highly expressing ACE2 and TMPRSS2 (“ACE2plus” and the subclone “ACE2plusC3”) are susceptible to infection with SARS-CoV-2, including the delta and omicron variants." (PMID 35891350, 2022). "The enhancement of viral replication of the Delta variant by TMPRSS2 corroborates with previous animal studies showing more extensive infection of alveolar pneumocytes for the Delta variant." (PMID 34951565, 2022). "For this, we generated control and USP22 KO Caco-2 cells that express the virus receptors ACE-2 and TMPRSS2 and are susceptible to infection with SARS-CoV-2 virus." (PMID 35933402, 2022). "Recent studies have shown that the furin and TMPRSS2 (furin/TMPRSS2)-dependent pathway plays a minor role in infection of the Omicron variant." (PMID 36243815, 2022). "Polymorphisms in the TMPRSS2 gene were analyzed regarding their involvement in SARS-CoV-2 infection, and some common variants seem to modulate TMPRSS2 expression, allowing a mild-to-moderate effect in infection susceptibility." (PMID 36012436, 2022). "We overexpressed hACE2 alone or together with TMPRSS2 in the KO cells and evaluated lenti-Spike infection and its susceptibility to imatinib." (PMID 35388061, 2022). "Histopathological and immunohistochemical analyses revealed that TMPRSS2 deficiency affects airway pathology after infection with the QHmusX strain." (PMID 36243815, 2022). "People without vaccination, with poor vaccine responses or with an increased risk for severe infection courses are likely to benefit most from TMPRSS2 inhibition, which at this stage ought to be initiated soon after exposure." (PMID 35871159, 2022). "The association of TMPRSS2 polymorphisms with COVID-19 infection provides not only a reason to evaluate the risk of infection but also a basis for possible prevention or treatment by TMPRSS2 inhibition." (PMID 36146782, 2022). "This was due to the fact that splice variations resulting from genetic variations in TMPRSS2 have modified the expression of TMPRSS2, altering susceptibility to infection with SARS-CoV-2." (PMID 36457338, 2022).
infection (continued). "These genes were significantly enriched in pathways associated with infection processes, providing further evidence that ACE2 and TMPRSS2 were co-expressed with genes associated with pathogen infection." (PMID 35154056, 2022). "The amount of viral load and receptor expression and the necessity of coexpression of both ACE2 and TMPRSS2 make the ocular tissue a low-risk site of infection." (PMID 35369001, 2022). "SARS-CoV-2 utilizes angiotensin-converting enzyme 2 (ACE2) and the membrane-bound serine protease TMPRSS2 for host cell entry Therefore, potential infection of tissues is linked to the expression of these enzymes." (PMID 35743381, 2022). "Compounds inhibiting TMPRSS2 protease activity have notably been associated with reduced infection activity of the SARS-CoV-2 Vpp." (PMID 34063247, 2021). "As an infection model, we used VeroE6/TMPRSS2 cell line that is highly susceptible to SARS-CoV-2 infection by constitutively expressing TMPRSS2, which is a host protease enhancing SARS-CoV-2 entry." (PMID 35095889, 2021). "Vero-TMPRSS2 cells were susceptible to the infection with WT and S gene mutant viruses, and S gene mutants showed a comparable or increased level of nascent viral N and full-length S proteins." (PMID 33476327, 2021). "The protease inhibitor camostat blocked SARS-CoV-2 infection across all susceptible cells, suggesting TMPRSS2 is the dominant protease that enables infection in the upper airway." (PMID 33507952, 2021). "At 3 days post infection, viruses with S gene mutations generated smaller plaques on Vero-TMPRSS2 cells compared with the parent (WT) strain." (PMID 33476327, 2021). "Lastly, since AAV vector is flexible in multi-gene delivery, the co-expression of non-canonical SARS-CoV-2 receptors and protein related to viral entry, such as CD147 and serine protease TMPRSS2, can be attempted to enhance mice susceptibility to infection." (PMID 34379705, 2021). "Remarkably, we found a significant association to a 1.73-fold increased infection risk for TMPRSS2 rs383510 CC genotype carriers in our German cohort." (PMID 33968142, 2021). "Accordingly, the priming of SARS-CoV-2 S protein by furin would hypothetically make many more cells susceptible to infection, as compared to S protein priming by TMPRSS2 alone." (PMID 33578849, 2021). "Immunofluorescence analysis revealed that Vero and Vero-TMPRSS2 cells were both highly susceptible to infection with WT and all S gene mutant viruses." (PMID 33476327, 2021). "From bone marrow aspirates of human healthy donors, we used our markers to isolate the three ERP populations by cell sorting, determine the expression of ACE2 and TMPRSS2, and evaluate their susceptibility to infection by SARS-CoV-2." (PMID 33581053, 2021). "In conclusion, we developed a cellular infection model system with optimal ACE2/TMPRSS2 ratio for high SARS-CoV-2 susceptibility, syncytia and CPE formation." (PMID 34394046, 2021). "The sulcular epithelium coexpresses ACE2 and TMPRSS2, and since the cell layer is thin, we believe that there is a high risk of internal infection." (PMID 32825469, 2020). "In the current study, we reasoned that population variation in upper airway expression of the ACE2 receptor for SARS-CoV-2 and the virus-activating TMPRSS2 protease would drive infection susceptibility and disease severity." (PMID 33046696, 2020). "Some studies highlight that the TMPRSS2 is an important element of the host cell as it is essential for spreading a great number of viruses causing potentially significant infections, as the influenza A and coronavirus." (PMID 33142764, 2020). "We recognized that the cells in culture exhibited a distribution of the expression levels of TMPRSS2 and Cathepsin B/L and thus had a distribution of susceptibilities to infection via the two pathways." (PMID 33290397, 2020).